STRBP (spermatid perinuclear RNA binding protein)
Description:
Involved in spermatogenesis and sperm function. Plays a role in regulation of cell growth. Binds to double-stranded DNA and RNA. Binds most efficiently to poly(I:C) RNA than to poly(dI:dC) DNA. Binds also to single-stranded poly(G) RNA. Binds non-specifically to the mRNA PRM1 3'-UTR and adenovirus VA RNA (By similarity).
Synonyms: SPNR; FLJ11307; HEL162; ILF3L; p74
Tractability: PROTAC: ubiquitination databases record sites on it; its protein half-life has been measured.
Gene: Protein-coding gene on chromosome 9 (123,109,500 to 123,269,102, reverse strand). Ensembl gene ENSG00000165209.
Subcellular location: Cytoplasm
Gene Ontology:
Molecular function: protein binding; RNA binding; double-stranded RNA binding; single-stranded RNA binding; microtubule binding; tubulin binding
Cellular component: nucleus; cytoplasm; manchette; microtubule cytoskeleton
Genetic constraint (gnomAD): Loss-of-function variants: 12 observed, 69.17 expected, observed/expected ratio (o/e) 0.17, 90% interval 0.11 to 0.28. The upper end of that interval is the gene's LOEUF score, 0.28, which puts it in group 1 of 6, group 1 being the genes least tolerant of losing a copy. Missense variants: 451 observed, 794.2 expected, observed/expected ratio (o/e) 0.57, 90% interval 0.52 to 0.61. Synonymous variants: 267 observed, 290.64 expected, observed/expected ratio (o/e) 0.92, 90% interval 0.83 to 1.02.
Homologues: Orthologues: chimpanzee STRBP (100% identical), macaque STRBP (99% identical), mouse Strbp (99% identical), rat Strbp (99% identical), dog STRBP (99% identical), guinea pig STRBP (98% identical), pig STRBP (95% identical), rabbit STRBP (95% identical), tropical clawed frog strbp (83% identical), zebrafish strbp (78% identical), Drosophila melanogaster Zn72D (25% identical), Caenorhabditis elegans zfr-1 (18% identical), and 3 more. Paralogues in human: ILF3 (59% identical), ZFR (28% identical), ZFR2 (27% identical), ILF2 (12% identical), ADARB2 (12% identical), ADARB1 (12% identical), ADAD1 (11% identical), ADAR (11% identical), ADAD2 (10% identical), ADAT1 (8% identical), STAU1 (6% identical), STAU2 (5% identical), and 2 more.
Diseases named in the same sentence as STRBP in open-access papers:
STRBP is named in the same sentence as 10 diseases in open-access papers, as found by Europe PMC text mining. Sharing a sentence is not in itself a finding about the gene and the disease. The quoted sentences say what the papers report.
lung adenocarcinoma (2 papers, 2020 to 2023). A carcinoma that arises from the lung and is characterized by the presence of malignant glandular epithelial cells. "According to reports, STRBP can be detected in lung adenocarcinoma, breast cancer, and hematological malignancies." (PMID 36968605, 2023). "Reports of rearrangements involving STRBP have been hitherto limited in solid tumors, e.g. STRBP-ASTN2 observed in lung adenocarcinoma and STRBP-ATG14 observed in breast cancer." (PMID 33505919, 2020).
Down syndrome (1 paper, 2019). "What is more, previous research demonstrates that STRBP at 9q33.3 is differentially expressed between patients with Down’s syndrome and controls." (PMID 31681408, 2019).
male infertility (1 paper, 2024). The inability of the male to effect fertilization of an ovum after a specified period of unprotected intercourse. "STRBP is expressed broadly in the testis, brain, and other tissues and plays a critical role in human spermatogenesis; loss of STRBP causes male infertility and premature death." (PMID 38346537, 2024).
Obesity (1 paper, 2021). Accumulation of substantial excess body fat. "On the other hand, monocytes from mothers with obesity (n = 3/time point) exhibited suppression of genes involved in interferon signaling (STAT1, GBP5, PSMB8) and response to reactive oxygen species (STRBP, HEBP2, TRAP1, TRPA1) (p value <0.001) with gestational age." (PMID 34195568, 2021).
pancreatic cancer (1 paper, 2024). "To evaluate whether the EMT-like changes are induced by STRBP depletion in pancreatic cancer cells, we established STRBP knockdown (KD) cells stably expressing shRNA for STRBP and STRBP KO cells in which the genomic locus of STRBP was deleted using the CRISPR-Cas9 system." (PMID 38346537, 2024).
tumor (3 papers, 2009 to 2024). "We have identified a novel tumor-promoting function of HSATII RNA, highlighting its propensity to form dsRNA through interactions with STRBP." (PMID 38346537, 2024).
STRBP also shares sentences with these, for which no sentence is quoted: infection (5 papers); breast carcinoma (1); hematological malignancies (1); Warthin tumor (1).